IFNG (interferon gamma)
Diseases named in the same sentence as IFNG in open-access papers (continued):
Sharing a sentence is not in itself a finding about the gene and the disease.
lung carcinoma (continued). "In addition to IFNβ and IFNγ, an investigation of early-stage lung cancer samples also found that GM-CSF is another enhancement factor that promotes neutrophils’ anti-cancer capacity." (PMID 38244071, 2024). "The recent spatial transcriptomic analysis of human lung cancer patients indicates that spatially organized ‘immunity hubs’ consisting of stem-like IFNγ+ T cells in residence with myeloid cells in a CXCL10/11-CXCR3 dependent manner are associated with positive response to anti-PD-1 therapy." (PMID 38786066, 2024). "Together, our results demonstrate that the delivery of anti-IFNγ antibody to the capillary site by CREKA-lipo-anti-IFNγ may be beneficial for cancer patients undergoing chemotherapy, which can be explored as a new strategy for the treatment of lung cancer." (PMID 37056922, 2023). "For example, identified immunostimulatory factors (e.g. IFNG in lung cancer) are associated with a negative prognosis, whereas immunosuppressive factors (e.g. FOXP3/IL10 in ovarian cancer) are associated with a positive prognosis." (PMID 36419893, 2022). "The level of IFNG was recognized as a biomarker for lung cancer patients receiving immunotherapies." (PMID 34603338, 2021). "Notably, pembrolizumab increased IFNγ levels in cultures from 9/11 lung carcinomas and 2/4 colon cancers." (PMID 33597595, 2021). "However, JAK/STAT3 and PI3K-AKT signaling pathways are responsible for IFNγ-induced PD-L1 induction and immune escape in lung cancer." (PMID 34445462, 2021). "Similarly, IFNγ treatment significantly increased PD-L1-lnc levels across all the lung cancer cell lines." (PMID 33849634, 2021). "Indeed, ex vivo study with CAF isolated from lung cancer showed how T cells up-regulates CD73 on CAF in lung cancer through IFNγ secretion." (PMID 34884993, 2021). "Besides, IFNγ and/or celecoxib, the cyclooxygenase-2 inhibitor, treatment constantly suppress tumor growth in mouse lung cancer models." (PMID 33224886, 2020). "In addition, KP-LC VIReST resulted in significantly enhanced IFNγ responses to all lung cancer cell lines and the KRAS epitope." (PMID 32903551, 2020). "IFNγ treatment in the presence of MEK inhibitors significantly enhanced MHC II induction across multiple lung cancer lines, with minimal impact on expression of either PD-L1 or MHC I. Inhibition of histone deacetylases (HDACs) also enhanced MHC II expression to a more modest extent." (PMID 32312906, 2020). "Of note, IFNγ responses induced by KPL 160424S cells, which was derived from the advanced lung cancer model and had the same driver mutations as KP-LC, was significantly lower compared to other lung cancer cell lines stimulation." (PMID 32903551, 2020). "We found that in murine lung cancer model, ANF induced infiltration of CD8+ T lymphocytes into tumor tissues and increased IFNγ and TNFα expression, suppressed lung cancer cell proliferation, prolonged life-span of the mice, and significantly enhanced the therapeutic efficacy of anti-PD-L1 antibody." (PMID 30850589, 2019). "In this study, we demonstrated that by altering responsiveness of murine lung cancer cells to IFNγ, we could define changes in the TME that regulate responsiveness to anti–PD-1 therapy." (PMID 31133614, 2019). "Here, we chose to examine the effect that TNFα and IFNγ stimulation may exert on the immunopeptidome landscape of lung cancer cells." (PMID 30833945, 2019). "Moreover, CD4+ T cells from healthy donors cocultured with SPC‐A1 cells (lung cancer cell line) resulted in a reduction in IFNγ expression after stimulation, an increase in DNA methyltransferases (DNMTs) and hypermethylation of the IFNγ promoter." (PMID 30039553, 2018). "Current literature suggests that the secretion of cytokines IL-10 and IFNγ from TAMs can up-regulate B7x on lung cancer and hematological malignancies like Non-Hodgkin Lymphoma (NHL), however our studies did not confirm this after assaying several different human and murine tumors." (PMID 29137299, 2017).
lung carcinoma (continued). "Interestingly, the surface expression of MHC-I, MHC-II, and PD-L1 was up-regulated in response to IFNγ more often in lung cancer cell lines sensitive to erlotinib, but only expression of PD-L1 was inhibited by erlotinib." (PMID 27467256, 2016). "In addition, it significantly inhibited the IFNγ induced overexpression of PD-L1 proteins especially in EGFR driven lung cancer cell lines (p<0.05)." (PMID 27467256, 2016). "Until recently, there was little data on whether lung cancer cells act directly on immune cells to induce hypermethylation of the IFNG promoter." (PMID 24244422, 2013). "These in vitro results suggest that promoter methylation may influence IFNG expression in lung cancer patients." (PMID 24244422, 2013). "Therefore, treatment of lung cancer through demethylation, which increases expression not only of tumor suppressor genes, but also of cytokine genes such as IFNG, help protect against tumors." (PMID 24244422, 2013). "PBMCs of 9 lung cancer patients and 9 healthy controls were collected and IFNG were detected." (PMID 24244422, 2013). "Interestingly, in vitro exposure to BaP, a prototype PAH, elicited hypermethylation of the IFNγ promoter and decreased IFNγ expression in Jurkat T cells and two lung cancer cell lines." (PMID 22562770, 2012). "In addition, IL-4Rα blockade in the presence of IFNγ + TNFα significantly enhanced the autologous T-cell mediated cancer cell killing as measured by Annexin V positivity of EpCAM-expressing lung cancer cells and promoted the cancer cell elimination induced by PD-1 blockade." (PMID 40091029, 2025). "In addition, IFNγ ex vivo production may serve as a biomarker for overall survival time in lung cancer patients further supporting extrapolation of the results of this ex vivo study to patients." (PMID 40342421, 2025). "In lung cancer, genetic variants in cytokine genes, such as IL6, IFNG, and TGFβ1, have been found to be associated with an increased severity of CRS after treatment with PD-1 inhibitors, suggesting that these biomarkers may help to predict the exacerbated inflammatory response." (PMID 40004863, 2025). "Single-cell RNA sequencing data from public lung cancer and glioma cohorts demonstrated that the expression of TPST2 was negatively correlated with genes associated with antigen presentation, which is one of the representative down-stream targets for IFNγ signaling." (PMID 39095793, 2024). "Since we found that irradiation specifically suppressed STAT1 and STAT3 phosphorylation in IFNγ-treated A549 cells in this study, we speculated that STAT3 caused radioresistance was mediated by overexpression and activation of mutated EGFR in lung cancer after survived in RT treatment." (PMID 34685495, 2021). "As Smac mimetics have been shown to be well-tolerated in early clinical trials, IFNγ and Smac mimetic combination therapy merits further investigation and may present a promising novel apoptosis targeted regimen for a subgroup of lung cancer cells with biomarkers to predict responses." (PMID 29946223, 2018). "Interestingly, inhaled IFNγ showed therapeutic efficacy in a murine model of lung cancer." (PMID 18801189, 2008). "In support of this model, pharmacological inhibition of IAP with birinapant synergizes with IFNγ to reverse STING expression and function to promote tumor cytotoxic T cell infiltration and induce apoptotic death of LKB1-mut lung cancer cells." (PMID 40057483, 2025). "In a lung cancer model, radiation has been shown to enhance CXCR3+ T cell activation in an IFNγ-dependent manner, via CXCL10 and ICAM-1." (PMID 38786066, 2024).
lung carcinoma (continued). "Our recent studies in EGFR mutant lung cancer cell lines and murine head and neck cancer cells demonstrated a TKI-stimulated IFNγ transcriptional response accompanied by increased chemokine expression." (PMID 36739466, 2023). "Th1 cells, which release tumor necrosis factor alpha(TNF-α), IL-2, and interferon gamma (IFN-γ), contribute to antitumor immune responses in lung cancer." (PMID 36776832, 2023). "In this review, we discussed different biomarkers related to the efficacy of ICIs and their potential prognostic value in lung cancer, including TMB, TILs, IFNγ, NLR, and the composition of the gut microbiota." (PMID 37108738, 2023). "CLDN6-TCAR T cells exerted potent and antigen-dependent IFNγ secretion and cytotoxicity against human CLDN6+ Colo-699-N lung cancer cells (left and middle)." (PMID 36923303, 2022). "We found that IFNγ simultaneously increased phosphorylation on STAT1 and STAT3 in EGFR-positive lung cancer, resulting in overexpression of PD-L1 (p < 0.05)." (PMID 34685495, 2021). "Granzyme B was considered a hydrolase enzyme leading to tumor cell apoptosis but IFNγ induced STAT3-mediated PD-L1 and MCL1 expression in EGFR-positive lung cancer cells." (PMID 34685495, 2021). "Several studies also suggested that IFNγ/STAT1 signal pathway plays a key role in inhibition of EMT in several cancers, including lung cancers, gallbladder cancer, hepatocellular carcinoma." (PMID 31113461, 2019). "The interaction between lung cancer cells and CD4+ T cells induces hypermethylation of the IFNG promoter in CD4+ T cells, which serve as a mechanism of tumor-induced immunosuppression." (PMID 24244422, 2013). "More importantly, to evaluate whether lung cancer cells could impact the methylation status of immune cells by down regulating IFNG expression, we established an in vitro transwell culturing system and then investigated CpG methylation of the IFNG promoter in CD4+ T cells." (PMID 24244422, 2013). "Studies on the impact of CXCR3 ligand in IL‐7/IL‐7Rα‐Fc–mediated antitumor activity revealed that when treating mice with lung cancer using IL‐7/IL‐7Rα‐Fc, it raised the levels of chemokine ligands CXCL9 and CXCL10, IFNγ, and IL‐12, but it reduced the levels of IL‐10 and TGF‐β." (PMID 39083441, 2025). "Mirroring data in urothelial cells, we found that the pro-T cell cytokines CXCL9/10/11 are strongly induced by a combination of IFNγ and EZH2 inhibition in both human and murine tumoroids, and that this gene cluster is a direct PRC2 target in human lung cancer cells." (PMID 38265267, 2024). "We examined eight key cytokines (Interleukin-1, IL-6, IL-8, IL-10, IL-12p70, monocyte chemotactic protein-1 (MCP-1), interferon-gamma (IFN-γ), and tumor necrosis factor-alpha (TNF-α)) in the plasma of 104 lung cancer patients and 48 cancer-free individuals using the FirePlex Immunoassay." (PMID 38276239, 2024). "For instance, IFNβ and IFNγ are two significant factors in TME that have been found to enhance the cytotoxicity of neutrophils, enabling them to combat early-stage breast cancer, lung cancer, and melanoma in both mouse and clinical models." (PMID 38244071, 2024). "In summary, these data suggest that KRAS-mediated inhibition of tumor-intrinsic IFNγ responses, which is required for effective antitumor immunity, may contribute to immune evasion in KRAS-mutant lung cancer." (PMID 38635884, 2024). "A few studies have shown that IFNγ induces EMT in prostate, renal, and lung cancer." (PMID 38729997, 2024). "High expression of the BC-specific ICD-derived metagene signature (TNF/CXCR3/P2RX7/CASP1/NLRP3/IL1B/LY96/CD4+/CD8+A/CD8+B/PRF1/IFNG/IL17A/IL17RA) is associated with prolonged overall survival (OS) in BC and OC patients but not in lung cancer patients." (PMID 37445860, 2023). "Finally, we extended our investigation to examine the effects of PTP 9 on the IFNγ response to a human colon cancer cell line, HT29, and a human lung carcinoma cell line, A549." (PMID 36968224, 2023).
lung carcinoma (continued). "For other subtypes of T cells, such as CD8+ cytotoxic T cells, T helper cells Th1 and Th17, several studies have suggested that interferon gamma (IFN-γ) from CD8+ cytotoxic T cells and Th1 could promote the stemness traits in lung cancer." (PMID 36293184, 2022). "In the present study, we used CCK assay and flow cytometry analysis and these data indicated that combination with IFNγ and STAT3 inhibitor could promote apoptosis and inhibit cell cycle transition to inhibit the proliferation of lung cancer cells." (PMID 36185620, 2022). "Taken together, these data indicated that combination with IFNγ and STAT3 inhibitor could inhibit the proliferation of lung cancer cells by promoting apoptosis and cell cycle transition." (PMID 36185620, 2022). "The activation markers GZMB, PRF-1, and IFNγ, migration marker CD183 (CXCR3), and inhibitory marker CD274 (PD-1), were measured and compared in CD8+ T cells with A549 co-cultured, chemokines treated, and patients with late-stage lung cancer." (PMID 34680466, 2021). "The interaction between CD4+ T cells and lung cancer cells could up-regulate expression of DNMT and methylation of IFNG promoter." (PMID 32296631, 2020). "In lung cancer, MHC II is expressed in both tumor-infiltrating lymphocytes (TILs) and tumor cells, and the expression in tumor cells could be induced by interferon-gamma." (PMID 31242643, 2019). "Whereas DNT-mediated cytotoxicity to leukemic cells was largely dependent on IFNγ and perforin/granzyme B, this was not the case for lung cancer as blocking these using similar protocols only modestly affected DNT-mediated cytolysis." (PMID 30670085, 2019). "In the human lung cancer cells, from which the CM was derived for the ex vivo culture, TNF, IL6 and IFNB1 were upregulated upon Snail OE, while IFNG was undetectable." (PMID 30190790, 2018). "Together, our findings suggest that chemotherapy may activate immune response mechanisms such as IFNα, IFNγ, STAT3, and TNFα in lung cancer, which may generate a favorable tumor microenvironment for subsequent response to checkpoint immunotherapy." (PMID 29871672, 2018). "Of note, also the expression levels of other putative tumor-derived cachexia-inducing signaling compounds (OSM, LIF, TNFα, IFNγ, PTHrP, ZAG, PIF, TWEAK, IL-1β, MSTN and INHBA) were tested for possible correlation between expression level and prognosis for lung cancer patients." (PMID 28515477, 2017). "The treatment with IFNγ up-regulated the surface expression of MHC-I, MHC-II, and PD-L1 more frequently on lung cancer cell lines sensitive to erlotinib than on those resistant erlotinib, suggesting that EGFR-driven lung cancer may be immunologically reactive." (PMID 27467256, 2016). "The release of inflammatory cytokines such as interferon-gamma (IFN-γ) activates the signal transducer and activator of transcription 3 (STAT3) pathway and subsequently upregulates PD-L1 expression on lymphoma and lung cancer cells." (PMID 25889536, 2015). "Our study suggests that interaction between lung cancer cells and CD4+ T cells induces DNMT expression and IFNG promoter hypermethylation in CD4+ T cell, which may serve as an important mechanism of tumor-induced immunosuppression." (PMID 24244422, 2013). "A significant negative correlation between IFNG plasma levels and total IFNG promoter methylation in CD4+ T cells of lung cancer patients was observed." (PMID 24244422, 2013). "Co-culturing SPC-A1 lung cancer cells and healthy CD4+ T cells induced DNMT expression and IFNγ promoter hypermethylation in CD4+ T cells, indicating a tumor-induced, DNA methylation-dependent suppression of IFNγ in lung cancer and highlighting the crosstalk between these processes." (PMID 34901003, 2021). "Furthermore, interferon-gamma (IFN-γ)-stimulated macrophages, which were referred to as M1 macrophages or M (IFN-γ) cells, could decrease mouse lung cancer growth by decreasing the M2/M1 ratio in tumor microenvironments." (PMID 33175182, 2021).
lung carcinoma (continued). "However, the splenocytes of mice immunized with Zfp760MT could not be stimulated to produce higher level of IFNγ secretion by lung cancer cells or candidate neoantigens." (PMID 39981234, 2025). "Additionally, Selumetinib also appears to attenuate PD-L1 expression without impeding interferon gamma (IFNγ)-induced MHC-I upregulation in nonsmall cell lung cancer cells, suggesting that it may also benefit patients receiving cancer immunotherapy." (PMID 31936067, 2020). "There was a minimal expression of MHC-II in all lung cancer cell lines tested, and this is anticipated as MHC II genes are not typically expressed in non-hematopoietic cells without an inflammatory signal such as IFNγ." (PMID 27467256, 2016). "Exposure of Jurkat T cells and lung cancer cell lines to BaP resulted in hypermethylation of a CGI in region 1 and specific non-CGI CpG sites in region 2 of the IFNγ promoter and reduced IFNγ expression, but these changes were significant only in cells treated with low doses (0.1 and 1 nM) of BaP." (PMID 22562770, 2012). "Therefore, we assessed a series of lung cancer cell lines with wide range of known sensitivity to erlotinib for the impact of EGFR inhibitors on MHC-I, MHC-II, and PD-L1 expression in the presence or absence of inflammatory cytokine, IFNγ." (PMID 27467256, 2016).